IL27 (interleukin 27)
Diseases named in the same sentence as IL27 in open-access papers (continued):
Sharing a sentence is not in itself a finding about the gene and the disease.
infection (continued). "Based on these evidences, we can envisage that the absence of IL-27 production from Mtb-infected monocytes could lead to a more efficient elimination of mycobacteria, which is crucial for the containment of the infection." (PMID 21197399, 2011). "The studies presented here show that infection with Toxoplasma gondii results in increased activity of HPSC and downstream progenitors associated with emergency myelopoiesis; however, in the absence of IL-27, HSPCs display a skewed developmental program that resulted in enhanced monopoiesis." (PMID 41396163, 2025). "Moreover, we assessed whether IL-27 controls IL-10 production by CD4+ T cells only in the spleen during infection or whether it exerts a dominant role in shaping the nonlymphoid CD4+ IL-10+ T cell response." (PMID 26459508, 2016). "However, this shift in the cytokine profile determined by IL-27 almost did not alter cell recruitment to the site of infection, as when comparing treated and non-treated animals only the presence of B cells in the peritoneal cavity significantly increased 72 h after IL-27 blockage in BALB/c mice." (PMID 27867384, 2016). "In addition, it is not clear so far whether IL-27 plays an important role in regulation of the immune responses during infections with extracellular protozoan parasites such as African trypanosomes." (PMID 26222157, 2015). "Thus, our data identify IL-27 signaling as a novel pathway to prevent the early mortality via inhibiting hyperactivation of CD4+ Th1 cells and their excessive secretions of IFN-γ during experimental infection with extracellular protozoan parasites African trypanosomes." (PMID 26222157, 2015). "However, IL-27 does not seem to play a direct role in exacerbation of S. aureus by influenza virus, as WT and IL-27Rα−/− mice had similar fold exacerbation of S. aureus secondary infection." (PMID 25651926, 2015). "This aberrant immune activation usually occurs in the absence of any obvious infection and includes elevated levels of cytokines such as CXCL10, IFN-γ, and interleukin-27 (IL-27) and increased expression of antiviral factors." (PMID 40333975, 2025). "Here we report IL-27 expression by macrophages was inhibited by blocking TLR-2 and -4, and infection with M. tuberculosis strain lacking TLR ligand LpqH lipoprotein." (PMID 36863206, 2023). "IL-33, IL-27, and TIMP-1 were lower than the limit of detection or showed no significant change from the mock infection model on both sides (data not shown)." (PMID 37725516, 2023). "Finally, ROC curve analysis demonstrated that IL-27 (p < 0.001 and AUC = 0.956) and IRF7 (p < 0.001 and AUC = 0.982) might be more important candidate for further studies in the field of finding probable biomarkers for filtering BK active infection from inactive ones." (PMID 34996392, 2022). "IL-27 was undetectable in the serum at any time point analyzed (between day 1 and day 30 postinfection) after LCMV Cl13 infection (data not shown)." (PMID 29593047, 2018). "While infection led to an expansion of LTHSCs, the numbers of LTHSC, granulocyte progenitors, and other progenitors (including common lymphocyte progenitors, common myeloid progenitors, and GMPs) (data not shown) were not impacted by the absence of IL-27." (PMID 41396163, 2025). "Furthermore, infection with M. tuberculosis strain lacking 19 kDa lipoprotein, putative M. tuberculosis TLR-2 ligand, produced less IL-27 as compared to wild type M. tuberculosis or M. tuberculosis complemented with the 19 kDa lipoprotein." (PMID 36863206, 2023). "Our study identified the critical window of CD4+ T cell activation and differentiation during Plasmodium infection that is targeted by IL‐27, in which its transient neutralization enhances memory CD4+ T cells and improves protection against challenge infection without exacerbated immune responses." (PMID 37855243, 2023).
infection (continued). "Differences in severity of infection regardless of viral load could account for these contradictions, however, further investigation into whether HIV impedes IL-27 production is needed." (PMID 35634328, 2022). "Within the first 5 days of infection, the absolute numbers of ILC2 did not significantly change in the dermis, which is in line with the unaltered expression of cytokines activating (IL-18, IL-25, IL-33, TSLP) or inhibiting ILC2 (IL-27, IFN-γ)." (PMID 35894051, 2022). "In both studies, independent of the intestinal site of infection, control of MAP infection correlated with local antigen-specific IL27 responses providing evidence this cytokine might provide a correlate of immune protection." (PMID 33329565, 2020). "We found not only that IL-27 instructs IL-10 expression by CD4+ IFN-γ+ T cells within the spleen during malaria infection, as previously shown, but also that it controls IL-10 production by CD4+ T cells in nonlymphoid tissues during infection." (PMID 26459508, 2016). "Thus, another important finding of this study is that, in the absence of IL-27 signaling, CD4+ T cells mediated mortality directly through their secretion of IFN-γ, at least, during infection with extracellular protozoan parasites African trypanosomes." (PMID 26222157, 2015). "Thus, our data highlight a critical and non-redundant role for IL-27/WSX-1 signalling in regulating the size and quality of the Th1 response during infection." (PMID 23593003, 2013). "In the chronic phase, Plasmodium‐specific CD4+ T cells in IL‐27‐neutralized mice consisted mainly of CD127+KLRG1− and CD127−KLRG1+ subpopulations that displayed distinct cytokine production, proliferative capacity, and are maintained in a manner independent of active infection." (PMID 37855243, 2023). "Whilst the role of IL-27 in controlling T cell apoptosis has not been directly examined, IL-6 and IL-12 are both known to exert anti-apoptotic effects on CD4+ T cells and concentrations of both these cytokines are significantly increased in WSX-1−/− mice during infection." (PMID 24244314, 2013).
tumor (206 papers, 2009 to 2026). "IL-27 has been associated with improved T helper 1 response and attenuated tumor growth in previous studies." (PMID 40254608, 2025). "Single-cell RNA-seq confirmed that IL-27 is expressed by myeloid cells, including tumor-associated macrophages (TAMs) and dendritic cells (DCs), and acts on all lymphoid cells that express IL-27R, including T and B lymphocytes as well as natural killers (NKs)." (PMID 40254608, 2025). "MDSCs also inhibit the CD40/IL-27 signaling in macrophages, increasing the risk of autoimmune conditions and tumor immunosuppression." (PMID 40872475, 2025). "The upregulated genes in PTCL‐TBX21 included Th1‐related genes, including CXCR3, CD38, INFG, CXCL9, CXCL11, IL27, and genes associated with tumor immunity, such as CD274 (PD‐L1), LAG3, and IDO1." (PMID 38234210, 2024). "Natural Killer (NK) cells and Natural Killer T (NKT) cells have also been implicated in the anti-tumor activity of IL-27." (PMID 37842640, 2023). "Significantly elevated IL‐27 levels have been observed in BC patients and are associated with tumour growth." (PMID 37649158, 2023). "According to their findings, treatment with Adeno-associated virus-expressing IL-27 led to the depletion of Tregs in the tumor microenvironment." (PMID 36742134, 2023). "Although IL-27 has been associated with both pro- and anti-tumor effects, elevated levels of IL-27 have demonstrated success in reducing cancer progression." (PMID 35529885, 2022). "Lastly, pan-cancer analysis of IL27 revealed that expression of IL27 was higher in tumor tissues and associated with a higher ESTIMATE score and expression of immune regulatory genes." (PMID 36713514, 2022). "Similar studies in human lymphoma cell lines showed that the enhancement of IL-27 expression by tumor cells triggered the surface expression of PD-L1 on tumor-associated macrophages." (PMID 33418929, 2021). "Similar studies showed the recombinant adeno-associated virus (rAAV)-mediated delivery of IL-27 reduced Treg frequency and increased the effectiveness of immunotherapeutic agents in different mouse tumor models." (PMID 33418929, 2021). "In ovarian cancer, neutrophil-derived IL-27 maintains the immunosuppressive phenotype of tumor-associated macrophages, by increasing ectonucleoside triphosphate diphosphohydrolase-1 (ENTPD1)/CD39 and PD-L1 expression, and IL-10 production." (PMID 32143355, 2020). "The Th2 immune phenotype can be reversed into the pre-existing Th1 immune phenotype through the induction of IFN-γ, interleukin (IL)-12, or IL-27, which subsequently causes tumor-suppressive effects." (PMID 33230218, 2020). "It is important to consider the impact of IL-27 on PD-L1 expression as increased PD-L1 expression is associated with dampening CTL tumor-specific immune responses." (PMID 31681561, 2019). "IL-27 overexpression prompts anti-tumor CTL responses in mice associated with increased proliferation, T-bet and IL-12Rβ2 expression, and production of IFN-γ." (PMID 25633106, 2015). "IL-11 belongs to IL-6 cytokine family, which consisted of IL-6, IL-11, IL-27, IL-30, IL-31, oncostatin M, and others, and it can be secreted by cancer-associated fibroblasts, myeloid cells, and tumor cell itself." (PMID 25929737, 2015). "The expression of the two IL-27 chains, IL-27A and EBI3, in tumor-associated leukocytes in EOC ascites and tumor tissues suggested a role of endogenous IL-27 in the microenvironment of this tumor." (PMID 26657115, 2015). "The enhancing role of IL-27 in generating anti-tumor CTL response was also demonstrated using IL-27R deficient mice." (PMID 24633175, 2014). "To examine the immunological effects of the loss of IL-27 signaling during the anti-tumor response, we isolated TDLN, NDLN and spleens from tumor bearing Il27ra+/+ and Il27ra−/− mice." (PMID 23554861, 2013). "Further studies are necessary to clarify the molecular mechanisms underlying IL-27 and poly(I:C)–mediated inhibition of tumor growth in TRAIL-dependent and -independent manners." (PMID 24155891, 2013).
tumor (continued). "Taken together, these data further indicate that IL-27 expression by tumor cells is associated with tumor progression." (PMID 24130734, 2013). "However, IL-27 also promotes tumor survival and growth through induction of regulatory T cells and modulation of tumor-associated macrophages through up-regulation of CD39 or PD-L1." (PMID 35780243, 2022). "Moreover, we revealed that IL27 was associated with higher T cell infiltration, hot tumor states, cytotoxic molecules and corresponding better therapeutic efficacy." (PMID 34733272, 2021). "The targeted IL-27 had higher bioactivity and activity in vivo in a recent study by our group, but the mechanisms underlying this effect had not been characterized in detail at the gene expression level on tumor cells." (PMID 32046108, 2020). "We recently reported that systemic delivery of IL-27 using recombinant adeno-associated virus (rAAV) induced depletion of Tregs and significantly enhanced the efficacy of cancer immunotherapy in a variety of mouse tumor models." (PMID 32292786, 2020). "Furthermore, IL-27 can be secreted by tumor cells and high IL-27 levels are associated with advanced cancer." (PMID 31681561, 2019). "Therefore, targeting different subsets of tumor associated cells by inhibiting IL-30 and IL-35, while promoting IL-27 signaling and production highlights the impact this cytokine triumvirate has on the fate of the TME." (PMID 31681561, 2019). "IL-27, produced by tumor-associated neutrophils, may induce CD39 expression and immune-regulatory activity in macrophages." (PMID 28255204, 2017). "Hence, preclinical studies utilizing immunodeficient mice injected with MM cells have shown that IL-27 reduces MM cell growth via suppression of angiogenesis, which causes ischaemic necrosis in tumours." (PMID 29089667, 2017). "By utilizing peptides, such as pepL, that bind to receptors upregulated in tumor cells, such as IL-6Rα, researchers aim to directly target the cytokine to tumor tissue and enhance the bioactivity of IL-27." (PMID 40078274, 2025). "The tumor-promoting effects of IL-27 have been observed in cancers such as ovarian, pancreatic, and breast cancers." (PMID 41254398, 2025). "A study published in Nature titled “IL-27 Elicits a Cytotoxic CD8+ T Cell Program to Enforce Tumor Control” revealed that IL-27 (interleukin-27), an important immune cytokine, has significant potential in regulating immune responses." (PMID 40963596, 2025). "A blockade of IL-27 activity or knockdown of coding the gene, was shown to stimulate tumor development, providing strong evidence that IL-27 is a crucial factor in supporting antitumor immunity." (PMID 40725022, 2025). "The neutralization of IL-27 via MDSCs’ inhibitory mechanism results in enhanced tumor progression, while blocking MDSCs results in IL-27 upregulation and delayed tumor progression." (PMID 40872475, 2025). "Interleukin-27 (IL-27) is a cytokine that can exhibit both anti-tumour and pro-tumour activities depending on the cancer type." (PMID 41296385, 2025). "For example, IL-27 predominantly mediates the regulation of inflammation within the tumor microenvironment through the downstream JAK/STAT3 pathway, thereby influencing tumor cell invasiveness." (PMID 40699663, 2025). "The role of IL-27 is particularly remarkable because it can both enhance the efficacy of anti-tumor T cells and produce a synergistic effect when used in combination with other ICIs, further improving therapeutic outcomes." (PMID 40963596, 2025). "IL-27 has been demonstrated to directly regulate IDO expression in tumor cells while stimulating tryptophan metabolite production, establishing a dual immunometabolic regulatory pattern particularly prominent in inflammatory microenvironments." (PMID 40642057, 2025). "Regardless, the observed effect of IL-27 has an unfavourable impact on the anti-tumour response, particularly in CLL, where both CD8+ T cells and NK cells play a critical role in eliminating malignant cells." (PMID 41296385, 2025).
tumor (continued). "Among these, IL-1β, IL2, IL6 play critical roles in activating immune cells and amplifying proinflammation responses, while TNFα and IL27 can directly inhibit the growth of tumor cells." (PMID 40046011, 2025). "Consistent with our results, it has been reported that IL-27 can enhance tumor-specific CD8+ T-cell expansion, program the memory T-cell differentiation of CD8+ T cells and increase CD8+ TEM production." (PMID 40350204, 2025). "In contrast, IL1A, IL11, and IL27 were downregulated, indicating their potential function as tumor suppressors." (PMID 40612864, 2025). "IL-27 was further confirmed to promote tumor-specific cytotoxic T cell responses and tumor regression in vivo." (PMID 40234384, 2025). "In an immunogenic model of colon tumor (MC38), the authors demonstrated that IL-27 blockade promoted tumor progression." (PMID 40254608, 2025). "Overall, in the context of cancer, IL-27 is mostly discussed as a pro-inflammatory cytokine that stimulates anti-tumor effects via activation of tumor-specific cytotoxicity." (PMID 39063193, 2024). "Studies in mouse models have demonstrated that IL-27 effectively inhibits fibrosarcoma and melanoma by enhancing NK cell-mediated anti-tumor responses." (PMID 39906735, 2024). "This bidirectional functionality allows IL-27 to maintain immune homeostasis across diverse pathological contexts, such as chronic inflammation, infections, and tumor microenvironments." (PMID 39906735, 2024). "For instance, DCs expressing FFAR2 inhibit their expression of IL-27 to sustain murine intestinal mucosal barrier integrity, reduce tumor bacterial burden, and suppress CD8+ T cell exhaustion, thereby restraining tumor initiation." (PMID 38903520, 2024). "When the mice bearing an SCCVII tumor were injected with IL-27, splenic DX-5+ NK cells killed more target cells." (PMID 38566992, 2024). "Conversely, 2‐ME‐treatment resulted in fewer CD163+ cells detectable in the TME, increased levels of tumor necrosis, increased IL‐10 plasma levels, and low IL‐6 and IL‐27 plasma levels." (PMID 38600057, 2024). "In oncology, IL-27 is often discussed as a potential agent capable of stimulating anti-tumor immunity." (PMID 39063193, 2024). "It has been reported that TIM-3 is transiently expressed on activated T cells both in vitro and in vivo due to the various tumor microenvironment cytokines, such as IL-27, a TIM-3 inducer." (PMID 39456930, 2024). "Splenic DX-5+ cells isolated from tumor-bearing mice were treated with IL-27, showing increased cytotoxicity against NK-sensitive YAC-1 cells." (PMID 38566992, 2024). "In the tumor microenvironment, IL-27 promotes the recruitment and activation of NK cells, contributing to the suppression of tumor growth." (PMID 39906735, 2024). "Various genes with tumor suppressor functions, such as chemokine ligand-11, IL-21, IL-27, CD40L, chemokine ligand-9, IL-9, and IL-15, were upregulated in DBMSCs after treatment with MDA231 cells in an IC setting." (PMID 39768220, 2024). "After intratumor injection, mRNAs of cytokines IL-12 and IL-27 within LNPs simultaneously reduced tumor size and increased the survival of mice, while enhancing tumor infiltration by CD45-positive leukocytes." (PMID 39508050, 2024). "The combination of IL-27 and cabo promoted the best anti-tumor response and the highest survival rates in mice." (PMID 37842640, 2023). "The data suggest that in the TME of immunotherapy responders, FCRL4+ FCRL5+ B cells are driven by IFNα, TNF, and IL27 signals, and Tfhs are activated by these B cells to enhance anti-tumor immunity through secreting IL21." (PMID 36869384, 2023). "An increase in IL-27 expression has been reported with anti-PD-L1 antibody treatment, leading to the suppression of tumor growth." (PMID 38026978, 2023).